ARHGAP31 (Rho GTPase activating protein 31)
Description:
Functions as a GTPase-activating protein (GAP) for RAC1 and CDC42. Required for cell spreading, polarized lamellipodia formation and cell migration.
Synonyms: CDGAP; AOS; AOS1
Tractability: PROTAC: its protein half-life has been measured.
Gene: Protein-coding gene on chromosome 3 (119,294,352 to 119,420,714, forward strand). Ensembl gene ENSG00000031081.
Subcellular location: Cell projection, lamellipodium; Cell junction, focal adhesion
Pathways (Reactome):
Signal Transduction: CDC42 GTPase cycle; RAC1 GTPase cycle; RHOA GTPase cycle; RHOU GTPase cycle
Gene Ontology:
Molecular function: protein binding; GTPase activator activity; SH3 domain binding
Biological process: regulation of small GTPase mediated signal transduction; small GTPase-mediated signal transduction; signal transduction
Cellular component: cytosol; lamellipodium; focal adhesion
Genetic constraint (gnomAD): Loss-of-function variants: 34 observed, 119.22 expected, observed/expected ratio (o/e) 0.29, 90% interval 0.22 to 0.38. The upper end of that interval is the gene's LOEUF score, 0.38, which puts it in group 1 of 6, group 1 being the genes least tolerant of losing a copy. Missense variants: 1,548 observed, 1,868.8 expected, observed/expected ratio (o/e) 0.83, 90% interval 0.79 to 0.86. Synonymous variants: 650 observed, 729.97 expected, observed/expected ratio (o/e) 0.89, 90% interval 0.83 to 0.95.
Homologues: Orthologues: chimpanzee ARHGAP31 (99% identical), macaque ARHGAP31 (95% identical), pig ARHGAP31 (84% identical), dog ARHGAP31 (83% identical), rabbit ARHGAP31 (81% identical), rat Arhgap31 (78% identical), mouse Arhgap31 (78% identical), guinea pig ARHGAP31 (77% identical), tropical clawed frog arhgap31 (45% identical), zebrafish arhgap31 (35% identical), Drosophila melanogaster CdGAPr (19% identical), Caenorhabditis elegans rrc-1 (9% identical). Paralogues in human: ARHGAP32 (24% identical), ARHGAP30 (19% identical), ARHGAP33 (17% identical).
Diseases named in the same sentence as ARHGAP31 in open-access papers:
ARHGAP31 is named in the same sentence as 49 diseases in open-access papers, as found by Europe PMC text mining. Sharing a sentence is not in itself a finding about the gene and the disease. The quoted sentences say what the papers report.
Adams-Oliver syndrome (11 papers, 2013 to 2022). Adams-Oliver Syndrome (AOS) is a rare disorder characterized by the combination of congenital limb abnormalities and scalp defects, often accompanied by skull ossification defects. "One of these genes, ARHGAP31, is known to be associated with Adams-Oliver syndrome that is characterized by scalp defects and distal limb reduction anomalies." (PMID 27598577, 2016). "The phenotypic expansion in our family cohort is intriguing due to the previous association of NOTCH1 and ARHGAP31 with Adams-Oliver syndrome (AOS)." (PMID 27760138, 2016). "Furthermore, ARHGAP31 and NOTCH1 have both been associated with Adams-Oliver syndrome (OMIM#100300, OMIM#616028), which is associated with severe cardiac malformations such as valvular defects and TOF." (PMID 27760138, 2016).
breast carcinoma (7 papers, 2017 to 2025). "ARHGAP31 (CdGAP) mRNA levels showed an overall negative correlation with total levels of E-cadherin protein in TCGA datasets, which was significant in stomach adenocarcinomas, ovarian cancer, colorectal adenocarcinomas, bladder and breast carcinomas." (PMID 28835688, 2017).
pancreatic carcinoma (2 papers, 2024). "Moreover, ARHGAP31 is not previously associated with pancreatic cancer, but has well-studied roles in actin modulation, since ARHGAP31 is the human orthologue for the mouse protein CdGAP (mCdc42 GTPase-activating protein) and ARHGAP31 inactivates the GTPases CDC42 and RAC1." (PMID 39110005, 2024).
prostate carcinoma (2 papers, 2021 to 2022). A carcinoma that arises from epithelial cells of the prostate gland. "Thus, this study presents data regarding CdGAP/ARHGAP31 as a gene associated with prostate cancer metastasis and a potential target in the treatment of aggressive prostate cancer." (PMID 34493786, 2021). "Therefore, to assess the clinical relevance of CdGAP in prostate cancer, we first determine whether CdGAP/ARHGAP31 expression is associated with BCR by analyzing publicly available datasets." (PMID 34493786, 2021). "In this study, we sought to investigate the role of CdGAP/ARHGAP31 in prostate cancer." (PMID 34493786, 2021). "Our data presented here outline the possibility that CdGAP/ARHGAP31, a negative regulator of Rac1 and Cdc42, acts as an oncoprotein rather than a tumor suppressor in prostate cancer." (PMID 34493786, 2021).
Aortic dissection (1 paper, 2025). Aortic dissection refers to a tear in the intimal layer of the aorta causing a separation between the intima and the medial layers of the aorta. "An additional recent GWAS on aortic dissection further highlights loci that appear to have differential expression across vascular sites (i.e., ARHGAP31 that we observe to have differential expression in fibroblasts across vascular sites)." (PMID 40931195, 2025).
aortic regurgitation (1 paper, 2016). "The father, carrying the loss of function variant in ARHGAP31 in family 4 (Family 4, I-1) was diagnosed with aortic valve disease, manifested as aortic regurgitation, bicuspid aortic valve and a slight dilation of the ascending aorta." (PMID 27760138, 2016).
celiac disease (1 paper, 2019). An autoimmune genetic disorder with an unknown pattern of inheritance that primarily affects the digestive tract. "This locus has also been reported as a susceptibility region for celiac disease, multiple sclerosis, systemic lupus erythematosus, and vitiligo, represented by rs11712165 in ARHGAP31, rs2293370 in TIMMDC1, and rs6804441 and rs148136154 in CD80, respectively." (PMID 30643196, 2019).
congenital heart defects (1 paper, 2021). "An additional three individuals were found to harbour pathogenic variants in genes associated with vascular abnormalities or congenital heart defects (TTN, NKX2-6 and ARHGAP31)." (PMID 34531397, 2021).
COVID-19 (1 paper, 2023). A disease caused by infection with severe acute respiratory syndrome coronavirus 2. "New target antigens such as ARHGAP31 are also emerging that are potentially related to COVID-19-associated autoimmunity." (PMID 37606433, 2023). "Interestingly, a region in the SARS-CoV-2 open reading frames 1a polyprotein showed significant physicochemical similarity to the autoreactive fragment of ARHGAP31, supporting the interpretation that enriched human peptides in post-COVID-19 samples are driven by SARS-CoV-2 antibodies." (PMID 37606433, 2023). "The autoantibodies identified in neuropsychiatric patients with COVID-19 and PCS are ARHGAP31, GAD65, acethylcholine receptor, D1/2, MOG, NMDAR, MCTP1, Yo, myelin, and Ma/Ta2." (PMID 37606433, 2023). "Activating-Rho GTPase-Activating Protein (ARHGAP31) was the major autoantigen identified in 22% of subjects with a prior SARS-CoV-2 infection and achieved enrichment with a 6-fold increase compared with the pre-COVID-19 controls." (PMID 37606433, 2023).
microcephaly (1 paper, 2021). A congenital or acquired developmental disorder in which the circumference of the head is smaller than normal for the person's age and sex. "We proposed that mutation of DOCK6 and ARHGAP31 genes could be the possible cause of FEVR associated with microcephaly." (PMID 33655927, 2021).
oral carcinoma (1 paper, 2023). "Further experimental evaluation is warranted to confirm the association of this infamous gene ARHGAP31 with the development of oral carcinoma." (PMID 37927751, 2023). "Rho GTPases are enzymes that regulate cell migration and invasion, and studies have shown that mutations in the ARHGAP31 gene may affect their activity, which may contribute to the onset and spread of oral cancer." (PMID 37927751, 2023). "It is crucial to keep in mind that oral cancer is a complicated condition that is influenced by a number of genetic and environmental factors and that the ARHGAP31 gene's function in this process is currently being investigated." (PMID 37927751, 2023).
syndactyly (1 paper, 2022). A disease characterized by the presence of syndactyly, including syndromic and non-syndromic forms. "Since ARHGAP31 is one of the causative genes identified for AOS, and FBLN1 variation has been shown to cause syndactyly, we highly suspected the two variations together contributes to the TTLD phenotype in the proband." (PMID 36176297, 2022).
tumour (3 papers, 2017 to 2023). "Particularly, mutations in the ARHGAP31 gene could result in enhanced RhoA GTPase activity, which might encourage tumour development and metastasis." (PMID 37927751, 2023). "Thus, future studies may be directed towards understanding the relationship between ZEB2 and ARHGAP31 proteins and their functions in the process of initiating treatment of tumours by performing functional analysis." (PMID 37927751, 2023).
cardiovascular disease (1 paper, 2022). "Six genes (TKT, TCF4, SWAP70, DDHD2, ARHGAP31, and LTB) showed significant associations of genetic variants with the risk of cardiovascular disease." (PMID 36204511, 2022).
ARHGAP31 also shares sentences with these, for which no sentence is quoted: cancer (8 papers); infection (3); osteosarcoma (3); aplasia cutis congenita (2); ovarian carcinoma (2); 22q11.2 deletion syndrome (1); adenocarcinoma (1); aortic valve disease (1); Beckwith-Wiedemann syndrome (1); Bicuspid aortic valve (1); bladder carcinoma (1); bone metastasis (1); breast invasive carcinoma (1); breast tumor (1); colorectal adenocarcinoma (1); colorectal carcinoma (1); coronary artery disease (1); fungal infection (1); genetic disorders (1); ischemia (1); Jacobsen syndrome (1); Kabuki syndrome (1); kidney diseases (1); leukemia (1); lipoma (1); melanoma (1); metastatic disease (1); multiple sclerosis (1); non-small cell lung carcinoma (1); prostate tumor (1).
A further 5 diseases each share a sentence with ARHGAP31 in 1 paper.